CD36 (CD36 molecule (CD36 blood group))
Diseases named in the same sentence as CD36 in open-access papers (continued):
Sharing a sentence is not in itself a finding about the gene and the disease.
metastatic cancers (4 papers, 2018 to 2024). A carcinoma which has spread from the original site of growth to another anatomic site. "Upregulation of several fatty acid transporter genes, such as FABP4 and CD36, has been reported in metastatic cancer." (PMID 37849907, 2021). "The model that can be delineated so far is that a high CD36 level correlates with metastatic cancers and thus is poorly prognostic." (PMID 30069479, 2018). "Furthermore, the CD36 gene was discovered to be often amplified in metastatic cancers, with the worst survival rates in the high-copy number group 15." (PMID 38370376, 2024). "Furthermore, CD36/SR-B2 was shown to be involved in the tumorigenesis of aggressive, metastatic cancers." (PMID 33917064, 2021).
morbid obesity (4 papers, 2016 to 2022). An excess of body weight, normally defined as an individual with a body mass index greater than 35 or a body weight greater than one hundred percent of ideal body weight. "Namely, chronic oversupply of fatty acids (present in morbid obesity) triggered an increase in CD36/SR-B2 and FATP4 protein content (total and cell surface), which translated to an increased LCFA influx (3H-palmitate uptake)." (PMID 35563741, 2022). "In human patients undergoing bariatric surgery for morbid obesity, the extent of hepatic CD36 downregulation after bariatric surgery correlates with improvements in steatosis." (PMID 30674978, 2019). "Interestingly, observed augmented expression of FAT/CD36 on different levels (mRNA and plasma membranes) in VAT compared to SAT in patients with morbid obesity may also confirm that VAT is more metabolically active tissue than SAT in this group of people." (PMID 29335416, 2018).
myeloid leukemia (4 papers, 2011 to 2021). A clonal proliferation of myeloid cells and their precursors in the bone marrow, peripheral blood, and spleen. "In these cases, the CD36+ LSCs also displayed an increase in uptake of FFAs and their subsequent oxidation, suggesting that CD36 can regulate LSCs metabolism in at least a subset of human myeloid leukemia." (PMID 30320108, 2018). "The pathways and genes that significantly changed were classified as follows: cancer pathways (EPAS1, CCND1, FGF13), myeloid leukemia pathways (ZBTB16, KIT, IL13), hematopoietic cell lineage pathways (EPOR, GYPA, CD36) and so on." (PMID 27516205, 2016). "In these cases, the CD36+ LSCs also showed an increase in FFAs and their subsequent oxidation, assuming that CD36 can adapt the LSC metabolism in at least one subgroup of human myeloid leukemia." (PMID 34692527, 2021).
Nephropathy (4 papers, 2014 to 2021). A nonspecific term referring to disease or damage of the kidneys. "CD36 levels correlate with development of diabetic microvascular complications, especially nephropathy." (PMID 28729885, 2017). "In our study, diabetic mice with nephropathy had the lowest level of expression of all three cholesterol transporters and this was accompanied by an increase in CD36." (PMID 25181357, 2014).
polycystic ovarian syndrome (4 papers, 2009 to 2016). "Recently, soluble CD36 in plasma was reported to be increased in type II diabetic patients and patients with polycystic ovarian syndrome." (PMID 19847289, 2009).
renal failure (4 papers, 2005 to 2025). "In addition, Kyoto Encyclopedia of Genes and Genomes (KEGG)-based functional enrichment analysis in the Kyoto encyclopedia showed that crotonylated protein was enriched in CD36, which is closely linked to renal failure." (PMID 34517817, 2021). "In cases of acute kidney injury, CD36 binds to FSP1, influencing its ubiquitination at K16 and K24 sites, leading to FSP1 degradation and induction of ferroptosis, thereby worsening kidney injury." (PMID 39881208, 2025). "Therefore, CD36 expression in PTECs is specifically associated with the diabetic condition and appears to be independent of degree of proteinuria and renal failure." (PMID 15737001, 2005). "However, only the B-class scavenger receptor CD36, a KEGG pathway, is closely related to renal failure." (PMID 34517817, 2021). "In addition, we did not observe increased proximal tubular CD36 expression in kidney biopsy samples from patients with FSGS, that were matched with DNP samples for the severity of proteinuria (all in the nephrotic range) and renal insufficiency (all with elevated serum creatinine; 1.7–5.0 mg/dl)." (PMID 15737001, 2005).
thrombosis (4 papers, 2020 to 2023). "Antibodies to CD36, a platelet glycoprotein, are associated with thrombosis, and anti-CD36 is highly prevalent in patients with aPL and with a trend to being more common in patients with recurrent thrombosis." (PMID 37580807, 2023). "Here we have provided multiple lines of evidence to indicate a role for CD36 in SARS-CoV-2 E protein-induced pro-thrombotic state that potentially underlies the coagulation and thrombosis disorders." (PMID 37604832, 2023). "Similarly, when deep venous thrombosis was induced in the IVC mouse model after the administration of E protein, the resultant average thrombus weight in CD36−/− mice were significantly decreased compared to those in WT mice." (PMID 37604832, 2023).
type 1 diabetes (4 papers, 2008 to 2021). "In this study, for the first time we established that FGF21 deletion is susceptible to develop DCM in STZ-induced type 1 diabetic mice, which is predominantly attributed to the exacerbated cardiac lipid accumulation via Nrf2 up-regulation of CD36-mediated cardiac fatty acid accumulation." (PMID 25823710, 2015). "However, it is uncertain whether or not type I diabetes (loss of insulin) induces the relocation of CD36 and resultant FA metabolism in the heart." (PMID 34940639, 2021).
Ureteral obstruction (4 papers, 2021 to 2025). Obstruction of the flow of urine through the ureter. "Interestingly, reduced lipid deposition and CD36 levels in the kidneys were detected in an SFN-treated unilateral ureteral obstruction-induced renal damage rat model." (PMID 37432260, 2023). "Additionally, the elevation in CD36, the primary fatty acid uptake system in the kidney, favors lipid accumulation in CKD models such as the unilateral ureteral obstruction model." (PMID 36358567, 2022).
α-Thalassemia (4 papers, 2011 to 2019). "Patterns of pRBC binding to ICAM1 were similar to those seen for CD36, with homozygous α+thalassemia being associated with significantly lower pRBC binding (1891.9; 1320.5–2565.7) in comparison to normal pRBCs (2858.2; 2057.1–3790.8; P = 0.007)." (PMID 25893206, 2014). "The reduction in adhesion observed in the SMA group was not due to the presence of polymorphisms such as sickle cell, α-thalassemia or CD36-deficiency as previously shown by other groups." (PMID 21390226, 2011). "However, as for CD36, these effects were reversed in pRBCs with co-inherited HbAS and α+thalassemia (lr test for interaction χ2 = 7.50, P = 0.024)." (PMID 25893206, 2014). "We investigated the effect of co-inherited HbAS and α+thalassemia on cytoadhesion of pRBCs infected with parasites of the ItG strain (which binds to both CD36 and ICAM1) in a total of 99 RBC samples of various Hb and α+thalassemia genotype combinations." (PMID 25893206, 2014).
Abdominal obesity (3 papers, 2014 to 2022). Excessive fat around the stomach and abdomen. "In this study, individuals over 30 years of age presented low soluble scavenger receptors levels pattern and CD36 gene subexpression, which suggest the chronic metabolic dysregulation in abdominal obesity." (PMID 27525284, 2016). "The aim of our study was to determine the association between CD36 and LOX-1 in presence of age and abdominal obesity." (PMID 27525284, 2016). "Individuals ≥30 years old with abdominal obesity presented high atherogenic index, lower soluble scavenger receptor levels, and subexpression of CD36 mRNA (54% less)." (PMID 27525284, 2016).
arteriosclerosis (3 papers, 2015 to 2023). A vascular disorder characterized by thickening and hardening of the walls of the arteries. "In the perspective of mechanism, ALDH2 plays an important role in the development and progression of arteriosclerosis by inhibiting oxidative low-density lipoprotein (ox-LDL)-induced foam cell formation via suppressing CD36 (cluster of differentiation 36) expression." (PMID 37355582, 2023). "Moreover, the prolonged daily injection of the CD36-favoring ghrelin derivate EP 80317 dramatically ameliorated the development of vascular lesions in the apoE−/− animal model of arteriosclerosis by lessening the CD36-driven endocytosis of oxidized low density lipoprotein (oxLDL) by macrophages." (PMID 33381011, 2020).
chronic lymphocytic leukemia (3 papers, 2018 to 2022). "CD36 seems to also play an important role in the biology of B-lymphoblastic leukemia (B-LL) and chronic lymphocytic leukemia (CLL), although little evidence exists." (PMID 36568966, 2022).
Cirrhosis (3 papers, 2019 to 2024). A chronic disorder of the liver in which liver tissue becomes scarred and is partially replaced by regenerative nodules and fibrotic tissue resulting in loss of liver function. "In the tissues of patients with cirrhosis, we found a statistically significant decrease in the expression of the CD36 gene, the encoding FA transporter, compared to the group without cirrhosis." (PMID 39125684, 2024).
demyelinating disorders (3 papers, 2020 to 2022). "Altogether, we show for the first time that CD36 is crucial for clearing myelin debris and suppressing neuroinflammation in demyelinating disorders such as MS." (PMID 32718316, 2020). "Our study provides the first evidence for an essential role of CD36 in the uptake of myelin and in controlling the inflammatory properties of phagocytes in demyelinating disorders." (PMID 32718316, 2020). "Thus, our findings show that CD36 plays a protective role in demyelinating disorders by driving the clearance of myelin debris and suppressing the induction of inflammatory phagocytes." (PMID 32718316, 2020). "Hence, targeting CD36 holds therapeutic promise for demyelinating disorders such as MS." (PMID 32718316, 2020).
dyslipidaemia (3 papers, 2012 to 2023). "Thus, CD36 has a broad implication in FA membrane transport and may possibly be involved in the metabolic aspects of dyslipidaemia." (PMID 22662181, 2012).
endometrial cancer (3 papers, 2022 to 2025). Primary or metastatic malignant neoplasm involving the endometrium (mucous membrane that lines the endometrial cavity). "Although CD36 is yet to be shown to be involved in the progression of endometrial cancer, FA uptake may still be crucial in its development." (PMID 35448537, 2022). "CD36 and SLC27A1 expression was examined in uterine fibroids and endometrial carcinomas of women." (PMID 39456882, 2024).
Granuloma (3 papers, 2010 to 2016). A compact, organized collection of mature mononuclear phagocytes, which may be but is not necessarily accompanied by accessory features such as necrosis. "On histopathological examination, there were fewer granulomas in the livers of Cd36-/- mice compared to the Cd36+/+ mice, but the microarchitecture of the granulomas appeared unchanged." (PMID 20950462, 2010). "In this model, the interaction of CD36 from one cell with phosphatidylserine on the surface of another, promotes the fusion of macrophages and generates giant cells similar to those observed in granulomas." (PMID 27280707, 2016). "Further evidence of intact adaptive immune mechanisms includes the universal survival of Cd36-/- mice, and the microscopic structure of granulomas, which were morphologically normal albeit reduced in number, commensurate with the reduced mycobacterial loads observed in these mice." (PMID 20950462, 2010). "Importantly, results from IHC and IF experiments suggested that while H37Rv- and BCG-induced granulomas from wild-type mice express elevated levels of JMJD3, ADRP and CD36, expression of these genes in granulomas from tlr2-null mice was significantly abrogated." (PMID 27532872, 2016). "Likewise, a recent study demonstrated a limited role for CD36 in controlling the outcome of M. tuberculosis pulmonary infection, with no survival difference and a modest effect on lung mycobacterial loads and granulomas only observed at early time points following intranasal challenge." (PMID 20950462, 2010).
head and neck squamous cell carcinoma (3 papers, 2023 to 2025). A squamous cell carcinoma that arises from any of the following anatomic sites: lip and oral cavity, nasal cavity, paranasal sinuses, pharynx, larynx, and salivary glands. "In head and neck squamous cell carcinoma (HNSCC), it has been reported that immunohistochemical (IHC) detection of CD36 expression makes it possible to differentiate false-negative lymph nodes in 18F-FDG-PET/CT imaging." (PMID 40508051, 2025).
hemorrhagic stroke (3 papers, 2017 to 2024). A stroke caused by a bleed on the brain. "CO altered circadian-dependent neuroprotection and CD36 induction, determining the functional outcome in a hemorrhagic stroke model." (PMID 38338958, 2024). "Due to CD36′s ability to bind thrombospondin and initiate platelet coagulation, it is evident that this receptor plays a crucial role in erythrocyte regulation and clearance after a hemorrhagic stroke." (PMID 33498620, 2021). "We recently identified a novel role for CO released via microglial HO-1 activity in response to hemorrhagic stroke in that microglial CO production not only mediates the clearance of blood but also regulates erythrophagocytosis via the expression of the scavenger receptor CD36." (PMID 38338958, 2024). "During a hemorrhagic stroke, the BBB is compromised, leading to an increased presence of CD36 in the brain." (PMID 33498620, 2021). "TSP-1 participates in angiogenesis, the inflammatory response, apoptosis, and fibrosis after hemorrhagic stroke through binding to various molecules including but not limited to CD36, CD47, and TGF-β." (PMID 29214179, 2017).
hypothyroidism (3 papers, 2020 to 2025). Abnormally low levels of thyroid hormone. "Overall, these results indicate that SCD1 deficiency increases FA uptake, in which PPARα and AMPK activation upregulate the FA transporter CD36, and oxidation in the heart in hypothyroidism." (PMID 33374300, 2020). "The hypothyroidism disrupts L-FABP, CD36, PEPT1, and GLUT2 circadian rhythms, reduces the MTTP amplitude, and punctually decreases the FATP4 content at the moment of the light to dark photoperiod transition." (PMID 39958687, 2025). "The effects of hypothyroidism (treatment factor) were significant for the content of MTTP, CD36, PEPT1, and GLUT2 proteins, while the interaction between time and treatment was significant only for L-FABP content." (PMID 39958687, 2025). "In mice, mild hypothyroidism brought about by dietary iodine restriction, results in elevated hepatic expression of lipid utilization genes including ACACA, FASN, and CD36." (PMID 38658325, 2024).
Impaired glucose tolerance (3 papers, 2013 to 2025). An abnormal resistance to glucose, i.e., a reduction in the ability to maintain glucose levels in the blood stream within normal limits following oral or intravenous administration of glucose. "Animal models further support this, demonstrating that high-fat diet (HFD)-fed mice exhibit upregulated CD36 expression on monocytes, a marker of monocyte activation, which is associated with impaired glucose tolerance." (PMID 40357304, 2025).
inflammatory bowel disease (3 papers, 2012 to 2021). A spectrum of small and large bowel inflammatory diseases of unknown etiology. "We have also assessed HIF-1α, p38-MAPK and CD36 immunostaining in the mucosa of patients with inflammatory bowel disease." (PMID 23119050, 2012). "Moreover, they suggest that CD36 expression in the damaged mucosa of patients with inflammatory bowel disease depends on p38-MAPK and HIF-1 activity." (PMID 23119050, 2012). "Immunohistochemical studies revealed CD36, HIF-1α and p38-MAPK expression in the mucosa of patients with inflammatory bowel disease." (PMID 23119050, 2012). "Furthermore, in the context of inflammatory bowel disease (IBD), enhanced serum levels of HMGB1 is accompanied by spontaneous IL-8 production by B-cells via interaction with TLR2 and CD36." (PMID 23519706, 2013). "Finally, we have analyzed the pathophysiological relevance of CD36 regulation by HIF-1 and p38-MAPK in the intestinal mucosa of patients with inflammatory bowel disease." (PMID 23119050, 2012). "In order to analyze the relevance of CD36 expression by HIF-1 in inflammation, we performed immunohistochemical studies of the damaged and non-damaged mucosa of patients with inflammatory bowel disease." (PMID 23119050, 2012).
liposarcoma (3 papers, 2019 to 2026). A usually painless malignant tumor that arises from adipose tissue. "Previous reports have addressed the expression of CD36 in liposarcomas 6, and our work provides information regarding the expression of SR-B1 in various phenotypes of soft tissue sarcomas, in order to distinguish between liposarcomas from non-lipomatous sarcomas." (PMID 31413752, 2019).
multiple myeloma (3 papers, 2017 to 2025). "It is worth noting that CD36 expression was, however, negatively associated with overall survival of multiple myeloma patients." (PMID 31022903, 2019).